NDST1 (N-deacetylase and N-sulfotransferase 1)
Diseases named in the same sentence as NDST1 in open-access papers (continued):
Sharing a sentence is not in itself a finding about the gene and the disease.
tumor (12 papers, 2010 to 2025). "Lymphatic endothelial deficiency in N-deacetylase/N-sulfotransferase-1 (Ndst1), a key enzyme involved in sulfating nascent heparan sulfate chains, resulted in altered lymph node metastasis in tumor-bearing gene targeted mice." (PMID 21172016, 2010). "Mutation/Deletion of NDST1 can target DC glycan sulfation, increasing the maturation of DC and inhibiting the process that trafficking of DCs to draining lymph nodes, thereby reducing the lung cancer tumor volume in mice." (PMID 38748047, 2024). "Another study suggested that NDST1 is associated with angiogenesis and tumor growth in lung tumors." (PMID 37508851, 2023). "The reduced presence of such cells along with a reduction in the frequency of tumor formation on the Ndst1f/f CD11cCre+ mutant background may point to a unique anti-tumor innate immunologic phenotype by Ndst1 deficient macrophages." (PMID 34715561, 2021). "We recently identified how a loss-of-function mutation in the glycan sulfating enzyme N-deacetylase/N-sulfotransferase-1 (Ndst1; involved in heparan sulfate biosynthesis) targeted to antigen presenting cells (APCs) may augment acquired anti-tumor T cell immune mechanisms." (PMID 34715561, 2021). "With these mechanisms in mind, the in vivo effects of a pan-endothelial deficiency in HS sulfation on regional lymph node metastasis suggested that a lymphatic-exclusive mutation in Ndst1 might also disrupt regional lymph node metastasis using the same tumor model." (PMID 21172016, 2010). "The demonstrated inhibition of HS biosynthetic system was mainly due to the selective significant suppression of the N-deacetylase/N-sulfotransferases Ndst1 and Ndst2 and sulfatase Sulf2 (-3–3.5-fold) in the tumor tissues." (PMID 37373391, 2023). "Among tumor-bearing mice, lymphatic vessel density in the lymph nodes from Ndst1 mutants was lower than that of their wildtype littermates, although the difference fell short of meeting statistical significance." (PMID 21172016, 2010). "This suggested that the specific loss of Ndst1 in the lymphatic endothelium reduced not only lymph node metastasis, but also the ability of CCL21 to associate with tumor cells in the lymph node sections." (PMID 21172016, 2010). "NDST1 can influence tumor T cell immune mechanisms, tumor Growth, tumor angiogenesis, etc." (PMID 38748047, 2024). "Alterations in the endothelial cell sulfate liver-associated gene NDST1 can selectively inhibit tumor angiogenesis without affecting physiological angiogenesis." (PMID 38748047, 2024). "Deletion of NDST1 in the lymphatic endothelium in vivo alters lymph node colonization by the tumor." (PMID 38748047, 2024). "Deletion of lymphatic endothelial Ndst1 resulted in a decreased xenograft tumor cell metastases to lymph nodes and oxazolone induced lymph node homing of DCs possibly via defective CCL21 oligomerization and/or promotion of CCR7-CCL21 interaction rather than anchoring to the matrix." (PMID 33717158, 2021). "In this study, we report that genetic alteration of lymphatic endothelial HS disrupts chemokine-dependent migration of tumor cells toward the targeted endothelium; and deletion of Ndst1 in the lymphatic endothelium in vivo is sufficient to alter lymph node colonization by tumor." (PMID 21172016, 2010). "This may also precede and possibly act independent of the anti-tumor potential of Ndst1 deficient DCs that appear to boost acquired cytotoxic CD8+ T cell responses against growing macroscopic carcinomas." (PMID 34715561, 2021). "The goal was not to examine carcinomatous tumor progression (with anti-tumor cellular immune effects under the CD11cCre+ driven Ndst1 mutation, as in prior work), but to assess whether a mutation relegated only to APCs alters the earliest steps in spontaneous tumor formation in situ." (PMID 34715561, 2021).
tumor (continued). "Pearson Correlation Analysis of gene expression among the 21 tumor samples revealed that EXT1 showed strong correlation to all the other enzymes (r > 0.8 for EXT2, NDST1, and HS6ST1)." (PMID 33585200, 2020). "Targeted deletion of Ndst1 in endothelial cells reduced the N-sulfate content of cellular HS and reduced tumor growth and tumor angiogenesis without affecting normal angiogenesis (wound healing)." (PMID 30564580, 2018).
cancer (11 papers, 2014 to 2025). A tumor composed of atypical neoplastic, often pleomorphic cells that invade other tissues. "HS metabolism-involved genes, such as NDST1, were studied to uncover cancer-related changes in the transcriptional pattern of the HS biosynthetic system." (PMID 38748047, 2024). "HPA analysis showed that the protein levels of LDHA and TES were highly upregulated in cancer tissues compared to normal pancreatic tissue, while those of NDST1, ANKZF1, and SIAH2 were significantly decreased in cancer tissues." (PMID 35935823, 2022). "For example, in the gastric carcinoma cell line MGC803, miR-191 targeting of NDST1 suppresses apoptosis and promotes cancer cell growth." (PMID 28672878, 2017). "N-deacetylase/N-sulfotransferase 1 (NDST1) is closely linked to migrasome, acting as both a specific marker and potential regulator, potentially playing a crucial role in cancer progression and offering insights for cancer therapy development." (PMID 40281132, 2025). "From this, we can also make some appropriate suggestions to speculate that the migrasome may play a role in regulating the biological process of related cancers above via mediating NDST1." (PMID 38748047, 2024). "NDST1 expression can also be epigenetically regulated via direct microRNA (miRNA) targeting, but the influence of miRNA-dependent regulation of NDST1 expression on cancer prognosis and progression seems to be context dependent (e.g., affected by experimental conditions, cancer and cell type)." (PMID 28672878, 2017). "Notably, much of the recent NDST1 research is focused on human cancer." (PMID 38748047, 2024). "For example, a shorter alternative splice form of NDST1 (“NDST1B”) is expressed at a low level in normal tissue but is overexpressed in certain cancers, where it might function in a dominant negative manner by replacing active endogenous NDST1 in the HS enzyme complexes during biosynthesis." (PMID 35294848, 2022). "There are various reports that genes involved in this interaction such as SLC25A39, NDST1, and RQCD1 regulate energy metabolism, chemoresistance, and the Akt signaling pathway, respectively, in cancer tissues." (PMID 38627780, 2024). "The results showed that ITGA5, NDST1, CPQ, ITGB1, PIGK, EOGT, and TSPAN4 had amplifications or deletions in most cancers." (PMID 36405728, 2022). "Transcriptional patterns of HS-metabolic enzymes (EXT1, EXT2, NDST1, NDST2, GLCE, 3OST1/HS3ST1, SULF1, SULF2, HPSE) were determined in normal, benign, and cancer human prostate tissues and cell lines (PNT2, LNCaP, PC3, DU145)." (PMID 24782989, 2014). "There are three marker proteins (NDST1, PIGK, and EOGT) of migrasome expressed in cancer." (PMID 38748047, 2024).
infection (4 papers, 2020 to 2024). The state of being infected such as from the introduction of a foreign agent such as serum, vaccine, antigenic substance or organism. "The results indicated that infection of NDST1 deficient cells resulted in a lower percentage of GFP+ cells over a wide range of MOIs." (PMID 32352982, 2020). "We observed that VACV plaques formed in NDST1+ cells contained a relatively tight center of closely packed infected cells surrounded by a small ring of more diffuse infection." (PMID 32352982, 2020). "In VACV infected cells, GFP was not detectable in most NDST1+ cells until 12–36 hours post infection and in most NDST1-/- cells until 24–48 hours post infection." (PMID 32352982, 2020). "During MYXV infection, GFP expression became detectable in the majority of NDST1+ cells between 2 and 6 hours post infection." (PMID 32352982, 2020). "While the results clearly indicated productive viral replication in both NDST1+ and deficient cells, significantly fewer infectious MYXV virions were observed in NDST1-/- cells at both 6 and 12 hours post infection." (PMID 32352982, 2020). "This reduction in binding affinity resulted in reduced rates of infection in NDST1-/- cells across a range of MOIs." (PMID 32352982, 2020). "To determine if this distribution of infection was solely responsible for the increased plaque sizes seen in NDST1-/- cells, we further quantitated the total amount of infection within individual plaques by analyzing overall GFP expression." (PMID 32352982, 2020). "In contrast, the total GFP content of VACV plaques was actually identical in both NDST1+ and deficient cells suggesting that the observed change in plaque size was due to an altered distribution of infection and not an actual increase in total virus present." (PMID 32352982, 2020). "Interestingly, infection with either virus at a high MOI (over 3) resulted in a near 100% rate of infection in both NDST1+ and NDST1-/- cells." (PMID 32352982, 2020). "While augmented T-cell mediated immunity induced by DCs may promote effector responses to facilitate viral clearance in the late/effector phase of infection by IAV, one of the consequences of upregulated IFN-β responses by Ndst1 mutant DCs may also be inhibition of viral replication." (PMID 35354833, 2022). "Consistent with the kinetics of poxviral replication, genomic viral DNA could not be reliably detected in NDST1+ cells until 6 hours post infection, at which point we observed a significant increase in signal for both MYXV and VACV genomes." (PMID 32352982, 2020).
vasculopathy (3 papers, 2010 to 2018). "Although this is the first study that specifically targets HS expression in the lymphatic endothelium, we have gained some insights from other work that has focused on vascular disorders associated with alterations in vascular Ndst1 expression." (PMID 21172016, 2010). "Thus, Ndst1 deficiency in the donor organ alone reduces both late (i.e., chronic) vasculopathy in aortic allografts and early or acute rejection in renal allografts." (PMID 30194334, 2018). "M-T1 and M3 inhibited WT (Ccr2+/+ and Ndst1+/+, p≤0.006) allograft vasculopathy, but did not block vasculopathy in Ccr2−/− (p = 0.61)." (PMID 20463901, 2010).
adenocarcinoma (1 paper, 2022). A common cancer characterized by the presence of malignant glandular cells. "The genes in selected metabolic pathways in adenocarcinoma cells potentially regulated by these ligands were predicted as follows: ETFB, HS6ST2, and NDST1." (PMID 35954218, 2022).
cardiovascular diseases (1 paper, 2019). "Suppression of NDST1 in endothelial cells results in reduced responsiveness to VEGFA, which plays important role in cardiovascular diseases." (PMID 31156544, 2019).
NDST1 also shares sentences with these, for which no sentence is quoted: Intellectual disability (2 papers); ischemic stroke (2); Lewis lung carcinoma (2); Alzheimer disease (1); anaplastic astrocytoma (1); Anxiety (1); astrocytoma (1); atherosclerosis (1); autism (1); autosomal recessive intellectual disability (1); bipolar disorder (1); Cyanosis (1); cyst (1); developmental delay (1); familial prion disease (1); gastric carcinoma (1); Gerstmann-Sträussler-Scheinker disease (1); glioma (1); glomerulonephritis (1); hemorrhage (1); Hyperglycemia (1); hypertriglyceridemia (1); liver cancer (1); meningioma (1); nephritis (1); neurodegenerative disease (1); neurodevelopmental disorder (1); peritonitis (1); prostate carcinoma (1); schizophrenia (1).
A further 3 diseases each share a sentence with NDST1 in 1 paper.